CD4 (CD4 molecule)
Diseases named in the same sentence as CD4 in open-access papers (continued):
Sharing a sentence is not in itself a finding about the gene and the disease.
tumor (continued). "A tumor-bearing mouse model showed tumor-infiltrating Treg cells can be converted from IL17A+FoxP3neg cells fostered by TGFβ and PGE2, which is consistent with our results about two Treg states and development pathways of naïve CD4+ T cell to TH17-like subsets and then Treg subsets in AML patients." (PMID 33648605, 2021). "Furthermore, overall CD8+ T cells in the peripheral blood (including non‐ITC) were significantly more clonal than the circulating CD4+ T‐cell pools, which could indicate these CD8+ T cells are tumor antigen specific." (PMID 34745610, 2021). "The mechanisms underlying the positive results involve modulation of the immune-inhibitory tumor stroma such as TGF-β down-regulation and M1 macrophage polarization, and promote infiltration and activation of anti-tumor effective cells such as NK and CD4+ T cells." (PMID 34621270, 2021). "Whether high levels of tumor-infiltrating T lymphocytes (both CD3+CD8+ and CD3+CD4+) in TME have long been recognized to have a favorable prognostic role, emerging insight into T cell biology indicates that the rescue of T cell homing at the tumor site is also essential for ICI efficacy." (PMID 34572771, 2021). "RT significantly increased OX40 expression on tumor infiltrating CD4+ non-Tregs and CD4+ Tregs." (PMID 34868010, 2021). "In vivo intraperitoneal injection of CD4+T cells from DLNs of CD4+NFAT5-KO (following three high salt stimulations) into day 21 orthotopic syngeneic tumors in wild type mice demonstrated a lack of anti-tumor response." (PMID 33918403, 2021). "Nor has there been much attention given to tumor-infiltrating CD4+ T cells." (PMID 34900690, 2021). "Due to data revealing PD-1 to be prominently expressed on CD4+ tumor-infiltrating lymphocytes (TILs) and to a lesser extent on CD8+ TILs, we could speculate that CD4+ T cells highly depend on glycolysis, while CD8+ T cells are able to better compensate low glycemic diets." (PMID 34830971, 2021). "Given the heterogeneous patterns of change in TIL subpopulations and the fact that the balance of immune-reactive versus immune-tolerant cells may be more relevant to deciphering the tumor immune contexture, the ratios of CD8+/FOXP3+, CD4+/FOXP3+, and CD3+/FOXP3+ in individual tumors were derived." (PMID 32852603, 2021). "These CD4+ CAR T cells also showed anti-tumour effector activity independent of CD8+ CAR T cells." (PMID 32457487, 2021). "CD4+ TCRαβ+ T helper cells (Th) are known to express the CD40L ligand that interacts with CD40 on dendritic cells, allowing secretion of several cytokines (IL-2, IL-15 and IFN γ) and activation of CD8+ cytotoxic T lymphocytes (CTLs), a T cell subset efficient in anti-tumor responses." (PMID 33668730, 2021). "CD4+ T cells were shown to have a negative role in tumor immunity and response to immunotherapy." (PMID 34638560, 2021). "In addition, IFN-γ-dependent interaction of CD4+ T cells with non-hematopoietic cells was shown to interfere with tumor angiogenesis." (PMID 34853796, 2021). "In addition, the therapeutic outcomes of the combinatory therapy correlated with increased tumor infiltration of CD4+ and CD8+ T cells, but not Tregs, compared to the control groups." (PMID 34206677, 2021). "In this study, we found that gMoxi at Zusanli could increase the proportion of NK cells in spleens and infiltration in tumours, but had no obvious effect on CD4+ and CD8+ T cells." (PMID 33506637, 2021). "Remarkably, PPD plus Zeb combination therapy enormously enhanced the infiltration of CD8+T and CD4+T cells, which indirectly indicated that PPD plus Zeb combination therapy could initiate an efficient anti-tumour immune response." (PMID 34795289, 2021).
tumor (continued). "When intra-tumoral CpG was combined with immunomodulatory T-cell antibodies it resulted in antitumor CD8 and CD4 T-cell immunity that, without the need for chemotherapy, treated massive and systemic lymphoma tumors, and resulted in permanent immunity against tumor relapse (Houot and Levy, 2009)." (PMID 34267616, 2021). "Enhanced infiltration of CD8/CD4 T cells with functional phenotypes in tumors after mRIPO may be due to T cell responses against immunogenic poliovirus antigens, rather than tumor-specific features." (PMID 33767151, 2021). "Finally, excessive lactate production by tumor cells and its release to the TME would also result in the inhibition of CD4+ T helper cells and NK cells, and activation and promotion of polarization towards an immunosuppressive phenotype of tumor infiltrating myeloid cells." (PMID 34503261, 2021). "Previous studies have incorporated epitopes from a single antigen to stimulate anti-tumour responses but few have used epitope combinations that could widen the applicability of vaccines to stimulate both CD4+ and CD8+ T cell responses and recognise multiple tumour cell populations." (PMID 34262856, 2021). "Hence, the concurrent expression of CD4+ and CD8+ co-receptor most likely provided additional survival signal for tumor-specific CD4+ T cells, which did not, however, translate into classical helper functions towards CD8+ T cells." (PMID 34759930, 2021). "Furthermore, the absolute numbers of tumor-infiltrating CD8+ T cells in MC38-inflicted tumors did not significantly differ between Cdk6fl/fl CD4-Cre and Cdk6fl/fl mice." (PMID 34248938, 2021). "In TIMER gene modules, NEFM transcriptional expression positively correlated with infiltration levels of CD8+ T cell, macrophage, neutrophil, and dendritic cell, and negatively correlated with infiltration level of B cell and tumor purity, whereas not with infiltration level of CD4+ T cell." (PMID 34001208, 2021). "Thus, the PD-1cKO mice, which enables deletion of Pdcd1 following tumor implantation and has normal baseline frequencies of EM CD4 and CD8 T cells, can be a useful model to investigate both tumor cell-intrinsic and tumor cell-extrinsic factors leading to regression of large tumors." (PMID 34912335, 2021). "Moreover, tumor tissues with higher infiltrating levels of T cells CD8, T cells CD4 naive, T cells CD4 memory resting, T cells regulatory (Tregs), T cells gamma delta, dendritic cells resting and neutrophils had lower level of AKR1C1 expression on cancer cells." (PMID 34702254, 2021). "Immunotherapy of lung cancer has been previously failed to introduce on the clinical practice, since it is lack of sufficient load of mutated tumor antigen, suppressed antigen presenting cells (APC) traffic from the tumor, as well lack of the specific biomarker signal for delivering CD4 T cells." (PMID 33633793, 2021). "Furthermore, the CD4+ and CD8 + populations increase with tumor grade and may correlate with poor survival outcomes." (PMID 34944036, 2021). "We observed no changes in the frequency of total CD4+ Tconv cells in the spleens or tumours of Ccr8−/− mice compared to Ccr8+/+ animals but did not in this study examine whether there were differences in the composition of the CD4+ Tconv compartment." (PMID 33838058, 2021). "We analyzed a variety of clinical factors that may be associated with CRS (gender, age, transplantation, CAR-T cell dose, bone marrow tumor burden, species of CAR, costimulatory molecules, serum maximum values of IL-6 and CRP, and minimum level of CD4/CD8) separately." (PMID 33708205, 2021). "Furthermore, GW4869 treatment could also increase the percentage of CD4+ and CD8+ T cells and impede tumor growth in mice subcutaneous tumor model." (PMID 34521440, 2021).
tumor (continued). "Compared to controls, SCCHN patients showed significantly increased activation status of CD4+ and CD8+ T cells, as well as a higher migratory potential of these lymphocyte populations, which might explain an increased infiltration into the tumor tissue." (PMID 34332614, 2021). "This can be shown by how Th17 and Tregs CD4 + T cell phenotypes play a central role in cancer, and how to the conditions within the tumor microenvironment (TME) can lead to a deregulation and hijacking of these T cell networks for tumor proliferation (Guéry and Hugues, 2015)." (PMID 34026764, 2021). "Tumor antigens derived from dead and dying tumor cells are processed by dendritic cells and presented by major histocompatibility complex class I and II molecules to antigen-specific CD8-positive (CD8+) and CD4-positive (CD4+) T-cells, respectively, which leads to immune activation." (PMID 34647108, 2021). "Following immunotherapy, the loss of CD8+ T cell targets has been documented, however, we do not know yet whether tumor antigens recognized by therapy-induced CD4+ T cells can also become altered or lost." (PMID 33546283, 2021). "However, the frequencies of CD8+ and CD4+ T cells expressing the cytotoxic molecules granzyme B or perforin were not elevated in the tumor or spleen of the anti-HVEM group." (PMID 34208480, 2021). "From the biological aspect, none of the CD3, CD4, and other immunophenotypes can be considered as a surrogate of the extreme heterogeneity and functional diversity of these lymphocytic populations in the tumor microenvironment." (PMID 34858823, 2021). "Importantly, an inverse CD4+ Tconv cells-to-CD4+ Tregs ratio, as well as a higher CD8+ T cell-to-CD4+ Tregs ratio, was observed after KV treatment in the tumor but not in tumor-dLNs." (PMID 34885215, 2021). "The effect of CD4+TN on tumor prognosis has not been unified." (PMID 34777388, 2021). "The CD4/CD8 ratio (T vs. CSD + T and T vs. CSD + T + CSD, both p < 0.05) and proportion of immunosuppressive CD11b+ myeloid cells infiltrating into the tumor microenvironment were markedly increased in CSD mice (T vs. CSD + T + CSD and T + CSD vs. CSD + T + CSD, both p < 0.05)." (PMID 34539666, 2021). "Although CD4+ Th cells are not the main effector cells of cellular immunity, CD4+ Th cells assist in activating CTLs and producing cytokines and chemokines that are indirectly involved in anti-tumor immune effects." (PMID 34692696, 2021). "Interestingly, CDR45RA + CCR7− effector CD4+ cells, which represent T central memory cells, were significantly less expressed in PD-L1 positive tumours compared to PD-L1 negative tumours (p = 0.01)." (PMID 34206956, 2021). "By comparing the effector function of senescent T cells from tumor and blood, we determined that regardless of their polyfunctional phenotype, tumor-infiltrating senescent CD4+ T cells exhibited a reduced effector function as highlighted by the lower frequency of cytokine-producing cells." (PMID 34386013, 2021). "In particular, they demonstrated that nanoparticles mediated photodynamic therapy (PTD), could induce potent antitumor immune responses via dendritic cells maturation; subsequent activation of CD4+T cells, CD8+T cells, and NK cells which inhibited tumor growth by killing or suppressing tumor cells." (PMID 33546290, 2021). "It has been described that TCR-activated Cd38−/− CD4+ T cells show a hybrid Th1/Th17 phenotype exhibiting intrinsically higher NAD+, enhanced oxidative phosphorylation, higher glutaminolysis, and altered mitochondrial dynamics that vastly improved tumor control." (PMID 34504495, 2021). "Indeed, cDC2 are able to cross-present tumor antigens and induce CD4+ T cell responses (including a Th2 phenotype) not relying on BATF3 DCs." (PMID 34032639, 2021). "In addition, the presence of TLSs significantly correlated with higher CD8/CD4 ratios in the tumor periphery, but not in the center of the tumor." (PMID 34553849, 2021).
tumor (continued). "Finally, expression of GGT7 was positively correlated with tumor purity (r = 0.317, P = 1.53e-9), CD8+ T cells (r = 0.254, P = 2.02e-6), CD4+ T cells (r = 0.216, P = 5.54e-5), macrophages (r = 0.323, P = 1.0e-9), neutrophils (r = 0.233, P=1.27e-5), and dendritic cells (r = 0.245, P = 5.0e-6)." (PMID 34513707, 2021). "Our current finding revealed that DPP-4i enhanced tumor-infiltrating MPO+, CD4+, F4/80+, Foxp3+ cells, and MDSCs, but decreased CD8+ T lymphocytes in metastatic sites, indicating that DPP-4i may induce tumor-immunosuppressive microenvironment by enhancing tumor-infiltrating immune-suppressive cells." (PMID 34631556, 2021). "Additionally, tertiary lymphoid structures (TLS) located near MCC also correlate with prolonged recurrence-free survival due to exceeded CD8/CD4 ratio in the tumor periphery, but not in its center." (PMID 34208339, 2021). "In the HPD group, there were fewer CD4+ effector T cells and CD8+ cytotoxic T cells (P < 0.010 and P < 0.382, respectively), whereas, there were significantly more regulatory T (Treg) cells co-expressing CD4+ and FOXP3+ in both the tumor and stroma (P < 0.003 and P < 0.015, respectively)." (PMID 33402127, 2021). "This is supported by our observation of an increase in CD4+ T cells in the nonirradiated tumor." (PMID 36405502, 2021). "Thus, T lymphocytes (CD4+ and CD8+) represented the main immune cell type in the peritumoral infiltrate, with cytotoxic T lymphocytes (CD8+) being the vast majority of these cells, with a rigorously spread pattern within the tumor tissue." (PMID 34692375, 2021). "Additionally, after adjusted by tumor purity, CTSF expression was shown to be positively correlated with immune infiltration of B cells (r = 0.212, p = 2.59e−06), CD4+ T cells (r = 0.179, p = 7.83e−05), Macrophage (r = 0.133, p = 3.38e−03), and DCs (r = 0.124, p = 5.93e−03) in LUAD." (PMID 34923982, 2021). "In addition, they showed that tumor-derived Gal-1 promotes an immunosuppressive breast cancer microenvironment by increasing the frequency of CD4+CD25+ Foxp3+ Treg cells within the tumor, draining lymph nodes, spleen, and lung metastases." (PMID 34680031, 2021). "Moreover, the CD4 subpopulation of CD3 T cells, which represent a diverse cell population with many differentiation states, including CD4+ Treg cells, was significantly higher in the non-tumor areas of Alk+Mad2 mice." (PMID 34885137, 2021). "Since CD4+ T cells play an important role in tumor immunity via promoting CD8+ T cell expansion, generating CD8+ T cell memory and priming the dual activation of CD4+ and CD8+ T cells might support anti-tumor efficiency." (PMID 33936075, 2021). "Moreover, activated CD4+ helper T lymphocytes upregulate the expression of major histocompatibility complex (MHC) molecules on the surface of tumor cells, thereby helping CTLs to recognize tumor cells and further induce cancer cell apoptosis." (PMID 34801032, 2021). "Although some recent studies showed that CD4+ T cells may act directly and indirectly in killing tumor cells, we did not incorporate this mechanism into our model." (PMID 34559809, 2021). "The non-sensitive tumors had higher levels of CD4+ T-cell infiltration than the sensitive tumors, suggesting that CD4+ T cell tumor infiltration may be a compensatory antitumor mechanism in non-sensitive tumors." (PMID 34868026, 2021). "However, a novel therapeutic gorilla adenovirus HPV vaccine, PRGN-2009, has shown promise when tested in PBMC-humanized NSG mice bearing human HPV16+ cervical tumors as it reduced tumor growth and increased CD8+ and CD4+ T cell levels in the TME, supporting its use in clinical trials." (PMID 34869042, 2021). "TILs isolated from tumors in many model systems, as well as humans with certain types of tumors, show skewed CD4+:CD8+ cell ratios with increased numbers of CD8+ T cells within the tumor, but not in the periphery (recall that normal peripheral CD4+:CD8+ ratios are about 2.5:1)." (PMID 33652752, 2021).
tumor (continued). "To test our hypothesis, we first defined the area of TLS-like lesion (see “Methods” section) and then evaluated the abundance of TFH-like (CXCL13+CD4+), B (CXCR5+CD20+), and TRM-like (CD103+CD8+) cells within the TLS-like lesions of archival tumor tissue samples using multiplexed IF." (PMID 34663810, 2021). "Also the altered CAR-T cell: tumor cell ratio led to the dysfunction of CXCR5 CAR as well as CD19 CAR-T cells from the third round of stimulation on accompanied by enhanced PD-1 expression on CD8+ and CD4+ CAR-T cells." (PMID 33431832, 2021). "Importantly, we uncovered that circHMGCS1–016 overexpression negatively regulates anti-tumor immunity through elevating the expression of CD73 and GAL-8 protein simultaneously, which further depressed CD8+ T cells and CD4+ T cells and reduced the anti-tumor activity of immune cells." (PMID 34526098, 2021). "We recently reported that in CD4+CD25+Foxp3+ T-regulatory (Treg) cells, Mef2d is required for the acquisition of an effector Treg (eTreg) phenotype and for the activation of an epigenetic program that suppresses the anti-tumor immune responses of conventional T and B cells." (PMID 34290714, 2021). "Collectively, these data demonstrate that the intrafollicular CD4 + T cells that drive outcome in FL are activated, nonexhausted effector memory T cells, a subset that is well-known to play a critical role in the immune response against the tumor." (PMID 34267181, 2021). "Moreover, Met@Man-MPs significantly enhanced the numbers of CD8+ T cells, activated CD8+CD69+ T cells, CD4+ T cells, and activated CD4+CD69+ T cells, while markedly decreased the numbers of MDSCs and Tregs in tumor tissues compared with free Met, Met@MPs and even high dosage of Met." (PMID 33469052, 2021). "An analysis of the tumor-infiltrating immune cells showed significantly decreased abundance of CD8+ T cells, resting and activated NK cells, and enhanced rates of resting and activated CD4+ T cells, regulatory T cells, and gamma delta T cells in the high-risk group." (PMID 34135913, 2021). "In addition, the depletion of CD8+ T cells and not CD4+ T cells reduced the anti-tumor effect of S-540956-adjuvanted vaccine." (PMID 35003132, 2021). "Moreover, there was a positive correlation between macrophage infiltration and tumor sizes in SAs, PRLs, and NFPAs; however, there were no such correlations with CD4+ T cells, CD8+ T cells, or MPO+ neutrophils." (PMID 33664865, 2021). "Intra-tumor combination of SLC and anti-CD25 mAb is an effective method for the treatment of HCC, which is related to the change of tumor microenvironment and the systematic optimization percentage of Treg, CD8+ T cells and CD4+ T cells in peripheral immune organs." (PMID 34869376, 2021). "To examine whether the small molecule drug Alphataxin exhibited effects similar to the α1PI plasma protein on circulating T cell numbers, we examined CD4+ T cells and CD8+ T cells by flow cytometry at baseline and during Alphataxin treatment in non-tumor-bearing male C57BL/6 mice." (PMID 34900690, 2021). "Therefore, it is likely that a combination of defective immune responses, which include increased Tregs, reduced CD4+CD103+ TRMs and increased inhibitory CD8+CD103+ TRMs, provides an immunosuppressive environment in cSCC, which permits subsequent tumor progression and metastasis." (PMID 33479027, 2021). "All together, we assumed that CD4+ T cells infiltration may be correlation with APE1 expression, and in particularly TNFRSF9+ Treg which belongs to CD4+ T cells influence prognosis in NSCLC given their biological functions during tumor progression." (PMID 33676448, 2021). "CD4 +T cells characterized by class II‐restricted and tumor‐specific has been validated to innately infiltrate in TME and exert anticancer duty with the assistance of CD8+ T cells or, with the secretion of type 1 cytokines, or with the direct killing of tumor cells CD4+ T cells." (PMID 34402193, 2021).